CD4 (CD4 molecule)
Diseases named in the same sentence as CD4 in open-access papers (continued):
Sharing a sentence is not in itself a finding about the gene and the disease.
COVID-19 (continued). "A two-sample MR analysis was performed to evaluate the causative influence of CD4+ TEM cell markers on PTB and COVID-19 utilizing the biggest GWAS summary-level data publicly accessible to date." (PMID 39337460, 2024). "As expected, COVID-19 patients had a robust expansion of plasmablasts, contrasting to lower proportions of major T-cell subsets (CD4 + and CD8+) than controls." (PMID 38454515, 2024). "h PLWH with at least one CD4+ Tcell count of < 200 cells/mm3 within 30 days before orafter contracting COVID-19." (PMID 39536214, 2024). "Recent studies have found that the activity of CD4+ T cells in COVID-19 patients is normal, but in this study, the immune auxiliary function of CD4+ T cells was inhibited." (PMID 38898888, 2024). "When CD4+ T-cell subpopulations were analyzed in acute COVID-19, there was a decrease in the proportion of Th17.1 and Th1 lymphocytes which are capable of IFN-γ production, as well as a slight decrease in circulating Treg levels." (PMID 38921725, 2024). "COVID-19 superinfection with Aspergillus fumigatus were more common in patients with severe COVID-19, comorbid chronic airway diseases, low CD4+T cell count, and the receipt of medium-flow oxygen therapy." (PMID 39240085, 2024). "As previously observed, after primary infection, both symptomatic and asymptomatic COVID-19 patients generate a robust CD4+ and CD8+ memory T cell response, in parallel with the humoral response." (PMID 38543865, 2024). "Despite the presence of significant immunodeficiency, as evidenced by the severe reduction in CD4+ T cells, the coinfected animals exhibited only mild COVID-19 symptoms, similar to the control group." (PMID 39066335, 2024). "We have further sequenced 1,815 blood samples from 1,521 COVID-19 cases with Adaptive TCRβ immunosequencing in order to identify a robust set of SARS-CoV-2 specific CD4 and CD8 TCRs from a fixed number of blood cells." (PMID 39840037, 2024). "We will describe the different features of SARS-CoV-2-specific CD4+ and CD8+ T cells generated in patients with mild and severe COVID-19 and compare them with Spike-specific CD4+ and CD8+ T cells induced by vaccination." (PMID 39460293, 2024). "This is consistent with studies in immunocompetent adults reporting induction of durable S-specific CD4+ T cells producing IFN-γ following mRNA COVID-19 vaccination." (PMID 38580714, 2024). "Although the complete understanding of disease pathogenesis remains elusive, it is widely believed that an aberrant and hyperactive immune response plays a pivotal role in the development of severe COVID-19, potentially involving CD4+ T cells." (PMID 39654887, 2024). "The percentage of CD4+ Tsens was negatively correlated with spike-specific antibody titers, neutralization ability, and COVID-19 reactive IL-2+CD4+ T cells." (PMID 38377029, 2024). "In conclusion, our results underscore the importance of incorporating immune monitoring with CD4+ T cell count and mHLA-DR into the prognostic evaluation of severe COVID-19 patients upon a full dexamethasone treatment course." (PMID 38762684, 2024). "It was indicated that patients with severe COVID-19 exhibit elevated levels of CD25+FOXP3+ Tregs within total CD4+ T cells with increased FOXP3 expression, which normalized in recovering individuals or convalescent patients." (PMID 39519310, 2024). "In contrast, another report found that patients with post-COVID-19 sequelae had reduced numbers of effector memory CD4+ and CD8+ T cells but increased expression of PD-1 (programmed cell death protein 1) on central memory cells." (PMID 39194726, 2024). "A similar accumulation of CD28−ve CD57+ve CD4 T cells was seen in severe COVID-19 convalescent patients." (PMID 38212801, 2024). "Titers of COVID-19 antibodies were lower for patients with CD4 cell counts of less than 200 cells/μL in the first, second, and third serological tests with statistical significance." (PMID 39772116, 2024).
COVID-19 (continued). "In the assessment of COVID-19 severity, the AUCs for CD4+ T cells and NLR were 0.715 (95% confidence interval [CI]: 0.645-0.784) and 0.741 (95% CI: 0.675-0.807), respectively." (PMID 39679195, 2024). "Of note, the strong cytotoxicity of TFK cells was evident in relation to TFH cells with a helper transcriptome, while it was obvious but minor in comparison to cytotoxic CD4+ TH1 cells in COVID-19 patients." (PMID 39025930, 2024). "COVID-19 mortality has been linked to a diminished ability to produce interferon-gamma (IFN-γ) and reduced early-stage activation of CD4+ and CD8+ T-cells." (PMID 39597537, 2024). "Recent studies suggest that T lymphocytes play a significant role in the pathological process of COVID-19, particularly in CD4 + T and CD8 + T cells." (PMID 38678181, 2024). "Especially within the lung, the main target organ for COVID-19, we detected significantly increased titers of activated CD4+ T cells, as shown for CXCR3+ cells." (PMID 38250865, 2024). "Elevated levels of soluble LAG-3, along with sTIM-3, s-GITR, sPD1, and sCTLA-4 were consistently higher in patients with severe and critical COVID-19, and these levels were negatively correlated with the absolute counts of CD4+ and CD8+ T cells." (PMID 39376569, 2024). "Across all three studies, we observed an enrichment and overall higher fraction of CD4+ T cells predicted to target this immunodominant epitope in repertoires from COVID-19-positive patients." (PMID 38615042, 2024). "In the critical patients of COVID-19, some researchers found that lymphocyte subsets were significantly decreased and CD4+/CD8+ T cell ratio remained normal." (PMID 38811907, 2024). "Later at D14–28, 16 cell subsets presented elevated global accuracy (AUC ≥ 0.8) to classify COVID-19 vs. HCs, with AUC = 1.0 registered for CD4+CD38+ and CD8+CD69+ and AUC = 0.9 observed for CD8+CD27+, CD3+CD107a+, CD4+T-bet+, CD8+CD107a+ and CD3+CD38+." (PMID 39597661, 2024). "Significantly higher percentages of unvaccinated asymptomatic COVID-19 patients with significant IFN-γ+CD4+ and IFN-γ+CD8+ T-cell responses specific to α-CCCs/SARS-CoV-2 cross-reactive epitopes were observed (p < 0.001)." (PMID 38605956, 2024). "In the study, we have found that pronounced lymphopenia and inverted CD4/CD8 ratio in severe COVID-19 patients were especially developed within the first month after infection." (PMID 39355257, 2024). "Only one (12.5%) participant from PWH cohort with CD4/CD8 of 0.68 required hospitalization due to complications of COVID-19 (p=0.0004)." (PMID 38812512, 2024). "We have found that pronounced lymphopenia and inverted CD4/CD8 ratio in severe COVID-19 patients were especially developed within the first month after infection." (PMID 39355257, 2024). "Using multivariate logistic regression analysis, we confirmed lower CD4+ T-lymphocytes as an independent predictor of COVID-19-related headache (p = 0.011)." (PMID 39274228, 2024). "Further reinforcing the relevance of pro-inflammatory myeloid cell activation and CD4+/CD8+ T cell dynamics in severe COVID-19, we observed relationships between these cell types and soluble mediators centrally implicated in COVID-19 severity." (PMID 38368384, 2024). "They reported that the induction of antigen-specific CD4+CD154+CD137+CXCR5+ peripheral TFH (pTFH) cells by the COVID-19 vaccine was higher in CVID sero-responders than in sero-nonresponders." (PMID 38921811, 2024). "In conclusion, we determined that PWH with normal CD4/CD8 ratio showed an excellent humoral response to COVID-19 vaccination based on high levels of IgG against SARS-CoV-2 S protein with enhanced neutralizing capacity in comparison with healthy donors." (PMID 38812512, 2024). "Metacluster #1 was more frequent in healthy donors than in COVID-19 patients and was characterized by CD4+ T cells expressing early differentiation markers (CD62L+CD95+CD127+CD28+) and low levels of KLRG1 and CD56." (PMID 39136010, 2024).
COVID-19 (continued). "On the other hand, a recent trial analyzing T cells from cirrhotic patients following COVID-19 vaccination showed that CD4+ and CD8+ T cells produce significantly lower levels of IFN gamma when exposed in vitro to spike protein peptides." (PMID 38675732, 2024). "The children with uncomplicated COVID-19 had higher CD4+GRB+/million CD3+ values (p-value: 0.02) compared to healthy controls." (PMID 39594853, 2024). "Male individuals were more likely to undergo CD4 testing during COVID-19 (OR 1.175; 95% CI 1.032 to 1.337) than female individuals." (PMID 39486827, 2024). "Here, median CD4 counts fluctuated over subsequent years, peaking notably with the highest median CD4 of any region, a year after the onset of COVID-19, in 2021 (near 500 cells/μL), before declining to around 350 cells/μL by 2023." (PMID 39066173, 2024). "MISC_A had lower CD4+CD8+IFNγ+/million CD3+ median (IQR) values compared to COVID-19 (p-value: 0.02) and controls (p-value: 0.03)." (PMID 39594853, 2024). "The available data show that HIV-infected individuals who have received ART and whose CD4+ T cell count is within the healthy range have good tolerance to the COVID-19 vaccine, but some differences have been reported in terms of immune effect." (PMID 38454994, 2024). "Comparing the age-matched Unexposed elder and COVID-19 convalescent, we found that the frequency of CD4+ T lymphocytes was lower in the COVID-19 convalescent than in the unexposed elder, and the frequency of CD8+ T cells did not change significantly." (PMID 38424104, 2024). "A meta-analysis that examined multiple risk factors across 23 different studies confirmed these findings by establishing associations between CD4 count and vaccine type with seroconversion in PWH following COVID-19 vaccination." (PMID 37821620, 2024). "We found that the SARS-CoV-2 vaccine induced a good immune response in PWH: a transient increase in CD4 count and CD4/CD8 ratio over a two-month window after COVID-19 vaccination." (PMID 39772028, 2024). "Comparing AAV patients before and after COVID-19 vaccination, naïve CD4 and CD8 T cells remain persistently low in the immunosuppressed groups both before and after vaccination compared to healthy controls (HC)." (PMID 38791279, 2024). "In regard to the adaptive immune response, CD4+ T-cell simultaneously exhibit both highly activated and exhausted stages in patients with severe COVID-19." (PMID 38863829, 2024). "Within the CD4 T cell pool there was a significantly lower frequency (p < 0.0001) and absolute number (p < 0.0001) of naïve CD4 T cells in the severe COVID-19 cohort." (PMID 38212801, 2024). "In conclusion, PWH hospitalized due to COVID-19 were older, had higher VS and CD4 + cell counts, and had lower mortality compared to those hospitalised due to non-COVID-19 causes, who more often were recently diagnosed with HIV and had ADEs." (PMID 38789972, 2024). "Studies have shown that COVID-19 patients often exhibit significant lymphocytopenia, particularly a decrease in CD4+ and CD8+ T lymphocytes, which are crucial for mounting an effective immune response against TB." (PMID 39100065, 2024). "From the comparison of the post-Spike antigen mix stimulation cytokine profile of MISC_A with the other three groups (MISC_C, post-COVID-19, and controls), significant differences were identified for CD4+IL-17+ and CD8+IL-17+ cells." (PMID 39594853, 2024). "Of note, PLH with CD4 counts ≥ 200 cells/mm3 were more likely to be vaccinated against COVID-19 compared to PLH with lower CD4 counts." (PMID 39066418, 2024). "Patients who have recovered from COVID-19 and individuals who have received a COVID-19 vaccination develop CD4+ and CD8+ T-cell immune responses specific to SARS-CoV-2, suggesting the possibility of durable T-cell immune responses." (PMID 39066390, 2024). "Kyoto encyclopedia of genes and genomes (KEGG) analysis indicated that the terms of CD4+ TEM markers were related to the occurrence of COVID-19." (PMID 39337460, 2024).
COVID-19 (continued). "We observed an increasing trend in CD4 count and CD4/CD8 ratio with extended vaccine doses, with PWH in the three-dose vaccine group having higher post-COVID-19 CD4 counts than those in the two-dose and one-dose groups." (PMID 39772028, 2024). "In contrast, strong CD4 and CD8 T-cell responses are reportedly associated with low disease severity in individuals with COVID-19." (PMID 39417078, 2024). "As was expected, patients with higher CD4 cell counts had higher titers of COVID-19 antibodies and lower hospitalization rate." (PMID 39772116, 2024). "Overall, our findings summarized a set of phenotypes feasible to be considered as potential predictors of COVID-19 outcome, including CD4+CD107a+, CD4+T-bet+, CD8+CD69+, CD8+T-bet+ and CD4+CD45RO+CD27+." (PMID 39597661, 2024). "Taken together, these results (i) demonstrate an overall higher magnitude of CCCs/SARS-CoV-2 cross-reactive CD4+ T-cell responses present in unvaccinated asymptomatic COVID-19 patients." (PMID 38605956, 2024). "S-specific CD4+ T cells are found in nearly all human subjects receiving two doses of mRNA COVID-19 vaccines, and memory CD4+ T cells are maintained up to 6 months after the second dose." (PMID 39460293, 2024). "Supporting this, we found B cell and CD4 T cell pathways enriched in ChAdOx1 nCoV-19 vaccinees compared with controls at COVID-19 onset, revealing rapid, vaccine-induced anti-SARS-CoV-2 adaptive immune responses captured in real-time." (PMID 38649734, 2024). "Low CD4 cell counts (<200 cells/μL) reduced the chances of normal and high titers of COVID-19 antibodies with an odds ratio of 0.27; p < 0.01 for normal antibody response and odds ratio of 0.304 for high antibody response; p = 0.001." (PMID 39772116, 2024). "COVID-19 has been linked to an escalation in HIV disease progression, marked by a decrease in viral suppression rates, a decline in CD4 counts and an increase in HIV-related mortality during the pandemic." (PMID 39486827, 2024). "In contrast, COVID-19 vaccines lead to establishment of relatively stable Spike-specific CD4+ T-cell memory pools, which are detectable up to 6 months post vaccination." (PMID 37821620, 2024). "Multinomial logistic regression was performed to examine the influence of other factors such as age, sex, previous COVID-19 infection, and last CD4 value on COVID-19 antibody titers." (PMID 39772116, 2024). "Elevated lactate dehydrogenase; C-reactive protein; age; and high expression of CD45+, CD39+CD45+, TIM3+CD39+CD4+CD45+, and TIM3+CD39+CD8+CD3+CD4+ cells were significantly associated with severe COVID-19." (PMID 38793691, 2024). "The outbreak of COVID-19 has also impacted routine viral load testing and CD4 counts, which are essential indicators for healthcare providers to monitor the response of PLHIV to ART and diagnose acute HIV infections." (PMID 39486827, 2024). "The findings underscore the need for continued efforts to vaccinate PLWH, particularly those with lower CD4 counts, to ensure broad protection against COVID-19." (PMID 39772116, 2024). "Similar results were detected in our study with patients in the acute phase of COVID-19, which showed an increase in NK cells and CD4+ T cells (20–30 days), but a decrease in CD8+ T cells up to 10 days and between 20 and 30 days from the onset of symptoms." (PMID 39483459, 2024). "The primary objective of this study was to assess the impact of COVID-19 vaccination on CD4 and CD8 cell counts, HIV viral load, and the durability of cellular immune response." (PMID 39772028, 2024). "When considering sociodemographic characteristics and clinical conditions, CD4 testing decreased during COVID-19 compared with prepandemic levels across sex, various age groups, functional statuses and WHO stages." (PMID 39486827, 2024).
COVID-19 (continued). "Nevertheless, a recent study demonstrated that COVID-19 vaccination can rapidly prime CD4 T spike-specific cells independently of antiviral therapy (ART), leading to a transient increase in CD4 count and a small drop in HIV viral load." (PMID 39772028, 2024). "This CD4+/CD8+ ratio is therefore a prognostic factor for the severity of COVID-19 and is rarely lower than 1.0 or higher than 2.5 in healthy patients." (PMID 40303184, 2024). "In summary, our study delineates CD4+ T cell senescence as a reliable immune signature predicting COVID-19 vulnerability in aged patients." (PMID 38377029, 2024). "Patients with CD8domBdep subtype had a longer COVID-19 duration of 9.1±4.0 days, compared with 6.8±2.8 days in CD8domB+ (P = 0.045), 6.0±1.5 days in CD4/CD8norBdep (P = 0.001), and 4.8±2.3 days in CD4/CD8norB+ (P = 0.001)." (PMID 38678181, 2024). "Not consistent with previous studies, although the expression of PD-1 on CD4+ T cells was elevated in myeloma patients with severe COVID-19, the expression of TIGIT was instead decreased during the acute phase." (PMID 39355257, 2024). "This study indicates that elevated levels of CD4+ T cells, particularly the CD4+/28+/192+ subset, correlate with poorer lung function outcomes post-COVID-19." (PMID 39768836, 2024). "Despite the important role of innate immunity, the best control of SARS-CoV-2 infection and protection from severe COVID-19 is achieved by a coordinated adaptive immune response made by virus-specific neutralizing antibodies (nAbs) and CD4+ and CD8+ T cells." (PMID 39460293, 2024). "Overall, the highest frequencies of CCCs/SARS-CoV-2 cross-reactive epitope-specific IFN-γ-producing CD4+ T cells were detected in the unvaccinated COVID-19 patients with less severe disease (i.e., severity 0, 1, and 2)." (PMID 38605956, 2024). "CD34 expression was lower in the COVID-19 group (p = 0.048), while CD4, CD68, and vimentin levels were higher in the COVID group (p < 0.05)." (PMID 39057113, 2024). "PLWH with COVID-19 had lower percentages of CD4+ T-cells (p < 0.001) and higher percentages of CD8+ T-cells (p < 0.001) than those without HIV." (PMID 39597537, 2024). "In contrast, severe COVID-19 patients exhibited expression rates of 17.2% in CD4+ T cells and 22.1% in CD8+ T cells." (PMID 38607373, 2024). "Similar to previous results, we identified depletion of NK and CD4 Naive cells with an increase in COVID-19 severity." (PMID 39712003, 2024). "In line with other studies, our research confirmed that PLWH with higher CD4 cell counts exhibited better immunologic responses to COVID-19 vaccines." (PMID 39772116, 2024). "A plausible mechanism contributing to reactivation is the depletion of CD4+ T cells in COVID-19 patients, which mediate the vital immune responses against mycobacteria." (PMID 40729284, 2024). "Immunization with a nanoparticle protein-based COVID-19 vaccine induces predominantly CD4 + T-cell response in Syrian hamsters." (PMID 38405749, 2024). "By contrast, we detected that CD39+CD45+ and TIM3+CD39+CD4+CD3+CD45+ were significant independent predictors for severe COVID-19." (PMID 38793691, 2024). "Patients with severe COVID-19 exhibit reduced CD4+ T cell counts,leading to prolonged viral replication and a higher susceptibility to secondaryinfections." (PMID 39536214, 2024). "The antibody response of PWH to COVID-19 vaccines is generally satisfactory, particularly in individuals with higher CD4 cell counts and undetectable viral loads." (PMID 39062187, 2024). "Adults who have recovered from COVID-19 have stable central memory CD4+ and CD8+ T cells directed toward a range of SARS-CoV-2 spike and nonspike epitopes." (PMID 39284068, 2024). "The analysis of memory T-cell profiles in COVID-19 patients has demonstrated that CD4+ and CD8+ T-cells are differentiated into Effector subsets during acute viral infections." (PMID 39597661, 2024).